EGFR (epidermal growth factor receptor)
Diseases named in the same sentence as EGFR in open-access papers (continued):
Sharing a sentence is not in itself a finding about the gene and the disease.
lung cancer (continued). "Examples include the impaired efficiency of EGFR inhibitor for lung cancer patients with heterogeneous driver status." (PMID 31409002, 2019). "KIT amp, EGFR amp, MET amp and ALK mutation in lung cancer, and CCNE1 amp in breast cancer were curated as resistant information only in the QCII." (PMID 31383922, 2019). "Association of EGFR kinase domain mutations with uncontrolled cell growth, proliferation, and migration have been reported in 32.9% of NSCLC and have proposed EGFR gene as the major oncogenic drug target in lung cancer." (PMID 31739412, 2019). "First, the data underscore the difficulty of harnessing CD8 T cell cytotoxicity in the context of poorly antigenic tumors like those present in these mouse models of EGFR mutant lung cancer." (PMID 31291990, 2019). "Given that EGFR is an oncogene in lung cancer, this can be a powerful clue to explain the exosome’s extreme tumorigenicity role in the neighboring microenvironment." (PMID 31686989, 2019). "Regarding the literature, different mechanisms of anti-EGFR TKI resistance have been extensively studied in lung cancer." (PMID 31546690, 2019). "Inarguably K-RAS and EGFR have been the focus of numerous studies which have tried to improve several aspects in lung cancer biology." (PMID 31739412, 2019). "Mutant EGFR-driven NSCLC tumours are nowadays the best-studied example of oncogenic addiction in lung cancer." (PMID 30959819, 2019). "This has led to FDA approved drugs for EGFR mutations, ALK rearrangements, ROS1 rearrangements, BRAF mutations, and NTRK rearrangements making up more than 20% of non‐small cell lung cancer patients." (PMID 31803961, 2019). "We showed that forced miR‐206 expression restored gefitinib sensitivity in IL6‐induced gefitinib‐resistant EGFR‐mutant lung cancer cells by inhibiting IL6/JAK1/STAT3 pathway." (PMID 31507089, 2019). "Collectively, our findings indicate DUOX1 deficiency in lung cancers promotes dysregulated EGFR signaling and enhanced GSTP1-mediated turnover of EGFR cysteine oxidation, which result in enhanced nuclear EGFR localization and tumorigenic properties." (PMID 30890751, 2019). "In the past few decades, it has been determined that the activation of EGFR is closely related to the genesis and progress of lung cancer." (PMID 31998131, 2019). "Enzyme-linked immunosorbent assay (ELISA) was performed to detect the EGFR-reactive IgG in lung cancer patients." (PMID 31722672, 2019). "By far, the epidermal growth factor receptor (EGFR)-signaling pathway is the best-known example in lung cancer." (PMID 30935143, 2019). "This review will mostly focus on the mechanism for EGFR endocytosis regulated by SNX1 trafficking in gefitinib-resistant human lung cancer cells." (PMID 35582586, 2019). "In acquired resistance to EGFR inhibitors, pAKTser473 level was elevated in lung cancer, and increased pAKTser473 level was suggested as a predictive biomarker for EGFR tyrosine-kinase inhibitors (TKIs) response." (PMID 30787334, 2019). "From transcriptomics data mining, we found that coordination between BZW1 and EGFR overexpression was correlated with a worse outcome for lung cancer patients." (PMID 31601833, 2019). "Elevated expression of EGFR is found in 62% of NSCLC and it is associated with poor prognosis as well as reduced survival rate in lung cancer patients." (PMID 31817718, 2019). "This study aimed to investigate the role of SCD1 inhibition by EGFR inhibitor (Gefitinib)-based anti-tumor therapy of lung cancer both in vitro and in vivo." (PMID 31019378, 2019). "EGFR tyrosine kinase inhibitors (TKIs) have been approved for the first line-treatment for EGFR-mutant lung cancer patients." (PMID 31993373, 2019). "Pneumatosis intestinalis is a rare adverse event that occurs in patients with lung cancer, especially those undergoing treatment with epidermal growth factor receptor tyrosine kinase inhibitors (EGFR-TKI)." (PMID 30819142, 2019).
lung cancer (continued). "Venugopalan and colleagues demonstrated that 24 h after TKI treatment, when extensive cell death is occurring, immune cell infiltration in the lungs of mouse models of EGFR mutant lung cancer is increased." (PMID 31291990, 2019). "There are other studies on colon and lung cancer cells which were sensitized with anti-EGFR TKIs for 24 h and 30 h, respectively." (PMID 31546690, 2019). "For example, in wild-type EGFR lung cancer cell lines A549 and H460, both Cbl-b and c-Cbl inhibited PD-L1 by inactivating STAT, AKT, and ERK signaling." (PMID 31882749, 2019). "Individuals with EGFR-mutant lung cancers in acquired resistance to TKIs demonstrated increased expression of AXL and, in some cases, also of its ligand GAS6." (PMID 31815659, 2019). "BIBW2992 inhibits ERBB2 and EGFR and targets at EGFR signaling pathway and has been widely investigated for cancers, like lung cancer and melanoma." (PMID 30972101, 2019). "We found that acquired EGFR-TKI resistance promotes the immune escape in lung cancer by upregulating PD-L1 expression." (PMID 31747941, 2019). "The role played by EMT in the resistance to lung cancer therapy has already been studied for EGFR-TKIs." (PMID 31531020, 2019). "A great deal of studies show that EGFR-target medicine made a huge breakthrough in treating cancer especially lung cancer." (PMID 31171012, 2019). "Based on these data, Arecoline-stimulated A549 lung cancer cell migration through mAChR3 transactivating the EGFR/c-Src/FAK pathway was confirmed." (PMID 30925742, 2019). "Specifically, EGFR T790 M, the mutation responsible for over 50% of the acquired resistance post-TKI in EGFR-mutated lung cancers, emerges in cis with the initial drug-sensitizing EGFR mutation in the tumour as well." (PMID 31703574, 2019). "Here, we investigated the effect of Arecoline on migration in lung cancer cell lines and its potential mechanism through the muscarinic acetylcholine receptor 3 (mAChR3)-triggered EGFR/Src/FAK pathway." (PMID 30925742, 2019). "In summary, our findings reveal a reciprocal regulation of miR‐206 and IL‐6/STAT3 pathway that mediates IL‐6‐induced gefitinib resistance in EGFR‐mutant lung cancer cells." (PMID 31507089, 2019). "KDM5A was also shown to mediate resistance to a second EGFR inhibitor called gefitinib, in EGFR-mutant lung cancer cell lines." (PMID 35582714, 2019). "Six human lung cancer cell lines with wild-type or mutant EGFR gene were exposed to pemetrexed and icotinib combined in different sequences." (PMID 30953548, 2019). "It has been reported that EGFR activation contributed to the upregulation of PD-L1 expression in lung cancers, and the expression level of PD-L1 can be decreased by EGFR-TKIs." (PMID 31747941, 2019). "Increasing evidence suggests that microRNAs are involved in EGFR-mediated signaling pathways in lung cancers, including miR-145, which is downregulated and associated with TKI resistance targeting ERK, AKT, Oct4, c-MYC, EGFR, and NUDT1." (PMID 31619200, 2019). "Recently, major advances in molecular diagnosis and targeted therapies have provided the opportunity to select lung cancer patients, and EGFR has become the new promising target." (PMID 31636509, 2019). "After short-term EGCG, the exposure of lung cancer cells was observed in that EGF-induced EGFR, Akt and ERK1/2 activation was substantially decreased." (PMID 31480720, 2019). "Although EGFR-TKIs are the standard first-line treatment for EGFR mutant lung cancer, the development of acquired resistance limits progression-free survival (PFS) to 10–12 months." (PMID 30625213, 2019). "Meanwhile, for the case BRAF non-V600E mutant lung cancer models, a disabled kinase signaling transduction was observed, where EGFR has the capacity to activate the MAPK cascade." (PMID 31652660, 2019). "In this study, we investigated the changes that occur within the immune microenvironment in a mouse model of EGFR mutant lung cancer after treatment with the TKI erlotinib." (PMID 31291990, 2019).
lung cancer (continued). "This study also suggests that synergistic therapy plays a role in the reversal of EGFR-tyrosine kinase inhibitor (EGFR-TKIs) resistance in lung cancer." (PMID 31109434, 2019). "Epidermal Growth Factor Receptor (EGFR) tyrosine kinase inhibitors (TKIs) like erlotinib are effective for treating patients with EGFR mutant lung cancer; however, drug resistance inevitably emerges." (PMID 31291990, 2019). "Aberrant up-regulation of miR-21 in lung carcinoma cell is found significantly correlated with phosphorylated-EGFR (p-EGFR)." (PMID 31139230, 2019). "Unfortunately, this study included only 13 EGFR mutant lung carcinoma, thus, providing limited information on the heterogeneity of this subtype of NSCLC." (PMID 30857358, 2019). "EGFR (also known as HER1 or ErbB1), a receptor tyrosine kinase, is commonly overexpressed in several types of cancer, including lung carcinoma." (PMID 30925736, 2019). "In lung carcinoma cells, the level of β1 integrin expression regulates the cell surface expression of EGFR and sustains its endocytic pathway." (PMID 31109009, 2019). "Experimental analyses of MR30 were performed in lung cancer cells representative of a disease for which EGFR inhibitors are indicated and melanoma cells deriving from a tumour type for which methyldiazonium generators such as dacarbazine and TMZ are indicated." (PMID 30416678, 2018). "Osimertinib—a third-generation EGFR-TKI—targets the T790M mutation and has demonstrated high efficacy against EGFR-mutated lung cancer." (PMID 30445769, 2018). "Activating mutations in EGFR, such as an exon 19 deletion, predict for the lung cancer cell sensitivity to erlotinib, an EGFR tyrosine kinase inhibitor." (PMID 30127519, 2018). "Inhibited growth and induced apoptosis of lung cancer cells by promoting epidermal growth factor receptor (EGFR) degradation." (PMID 30410443, 2018). "NEDD4 mediates the EGFR lung cancer cell migration signaling through promoting lysosomal secretion of cathepsin B." (PMID 29455656, 2018). "On the other hand, overexpression of HGF was identified in 61% of lung cancer patients with resistance to EGFR-TKIs overlapping MET amplification." (PMID 29890660, 2018). "The development of epidermal growth factor receptor (EGFR)-targeted tyrosine kinase inhibitors (TKI) led to a different molecular pathology classification in terms of targeted therapies for lung cancer." (PMID 29298713, 2018). "In contrast to this, overexpression of HGF is seen in a significant number of lung cancer patients with EGFR-TKIs-resistance overlapping MET amplification." (PMID 30469509, 2018). "Differences in clinicopathological features between Mt and EGFR wild-type adenocarcinoma of the lung (Wt) have recently been examined among resectable lung cancers." (PMID 30290774, 2018). "In a cohort of patients bearing EGFR mutant lung cancers, increased peripheral natural killer cells and INFγ were observed after 4 weeks of gefitinib treatment while circulating IL6 levels were decreased, especially in those patients sensitive to gefitinib." (PMID 29458371, 2018). "Although the specific reasons for these differences were unclear, biomolecular studies suggested that the more favorable prognosis of patients with 19 Del lung cancer was due to better responses to EGFR - TKI by 19 Del lung cancer than by L858R lung cancer." (PMID 30290774, 2018). "Aberrantly activated EGFR affects a wide range of human cancers, particularly lung cancer, colorectal cancer, pancreatic cancer and glioblastoma." (PMID 30016965, 2018). "In conclusion, our research demonstrated that in lung cancer EGFR‐TKI‐resistant HCC827‐GR and PC9‐GR cells, combination treatment with efatutazone and T0901317 produced a synergistic effect." (PMID 29573196, 2018). "MET amplification occurs in approximately 2-4% of patients with lung adenocarcinoma, higher in other histologic types of lung cancer, and up to 22% of patients with acquired resistance to EGFR inhibition therapy." (PMID 29568386, 2018).
lung cancer (continued). "Our data indicate that TAR RNA-bearing exosomes activate the ERK1/2 cascade in association with EGFR and TLR3 to promote proliferation, migration, and invasion of HNSCC and lung cancer cells." (PMID 30389917, 2018). "Loss of NF1 has been reported to result in resistance to various targeted tyrosine kinase inhibitors in a number of settings, including BRAF-mutant melanoma and EGFR-mutant lung cancer." (PMID 29435137, 2018). "Heterodimerization between IGF1R and epidermal growth factor receptor (EGFR) mediates the activation of bypass signaling, leading to resistance to gefitinib and erlotinib in lung cancer." (PMID 29455661, 2018). "More importantly, NEDD4 mediates both the EGFR-dependent and -independent secretion of lysosomal cathepsin B, which in turn promotes lung cancer cell migration." (PMID 29455656, 2018). "Since, for example, epidermal growth factor receptor in lung cancer was shown to influence the preferred anatomical distribution of BM, future studies should elucidate the influence of those factors on the perfusion pattern or vice versa." (PMID 29899729, 2018). "Aberrant activation of epidermal growth factor receptor (EGFR) signaling pathway has been identified to advance lung cancer tumorigenesis and results in the increase of patients mortality." (PMID 29681982, 2018). "Propolin C-regulated EMT was through downregulation of EGFR-mediated PI3K/Akt and ERK signaling pathways in EGFR-mutated lung cancer cells." (PMID 29681982, 2018). "The clinical outcomes of patients with a CNS metastasis from an EGFR‐mutant lung cancer have thus improved with the emergence of osimertinib." (PMID 30350450, 2018). "In conclusion, EGFR rs712829, rs2072454 SNPs, and TCCG haplotypes are associated with a risk of lung cancer among Jordanians." (PMID 30011810, 2018). "We identified clinical, demographic, and regional predictors of EGFR & KRAS testing among Medicare beneficiaries with a new diagnosis of lung cancer in 2011–2013 claims." (PMID 29554880, 2018). "Unfortunately, patients with EGFR mutant lung cancer develop disease progression after a median of 10 to 14 months on EGFR TKI." (PMID 29455650, 2018). "EGF-induced PI3K/Akt and ERK activation was inhibited in propolin C-repressed EMT in EGFR wild-type lung cancer cells." (PMID 29681982, 2018). "The increased expression and activation of c‐MET in response to EGFR TKIs and cytotoxic anticancer agent contribute to drug resistance in lung cancer cells through compensatory enhancing of Akt signaling." (PMID 29570930, 2018). "This is not surprising since these patients have acquired mutations during the course of the disease (EGFR T790 M) and the fact that this dataset includes fusions (ROS1, ALK in lung cancer, ABL1 in leukemia)." (PMID 29544535, 2018). "The findings are significant as previous gene amplification had been shown to vary upon ethnicity such as epidermal growth factor receptor in lung cancer patients of Asian ethnicity." (PMID 29351293, 2018). "Mutual exclusiveness between KRAS and EGFR mutations led to the three classifications of lung cancer groups: KRAS mutants, EGFR mutants, and KRAS/EGFR wild type." (PMID 29504894, 2018). "To summarize, our observations revealed that the exon 19 deletion mutant of EGFR is constantly internalized and routed through endosome to lysosome for degradation in lung cancer cells." (PMID 29976202, 2018). "Future studies that include more patients, other SNPs in EGFR, and clinical factors of lung cancer are strongly recommended." (PMID 30011810, 2018). "Clinical studies showed that lung cancer patients who are former or current smokers, are more resistant to EGFR TKIs." (PMID 29570930, 2018). "Our study offers a potential treatment for many lung cancer patients, who sequentially develop resistance to first‐, second‐ and third‐generation EGFR inhibitors." (PMID 29212784, 2018).
lung cancer (continued). "EGFR has become an important therapeutic targetfor the treatment of lung cancer because more than 60% of non-small cell lung carcinomas (NSCLCs) express EGFR." (PMID 30108422, 2018). "Central nervous system (CNS) metastasis is one of the serious complications of epidermal growth factor receptor (EGFR)‐mutant lung cancer, which arises due to poor penetration of the brain–blood barrier by EGFR‐tyrosine kinase inhibitors (EGFR‐TKIs)." (PMID 30350450, 2018). "The combination of anti-estrogen fulvestrant and an EGFR-TKI such as gefitinib or erlotinib can maximally inhibit lung cancer cell proliferation, induce apoptosis and reduce downstream signaling pathways both in vivo and in vitro." (PMID 30356721, 2018). "In transgenic mouse models of lung cancer, Dusp6 RNA was present at significantly higher levels in the lungs of mice bearing tumors driven by mutant EGFR or KRAS transgenes than in normal mouse lung epithelium." (PMID 30475204, 2018). "We have however applied our NUFSTMtechnology to produce a water‐soluble, nano‐particulated erlotinib, NUFS‐sErt, which showed a comparable efficacy to its parent compound against EGFR‐mutant lung cancer cell lines." (PMID 30350450, 2018). "The epidermal growth factor receptor (EGFR) is closely implicated in cancer, and sequencing analyses have revealed a high mutation rate of EGFR in lung cancer." (PMID 29976202, 2018). "On the other hand, it was also shown that the IL‐6/JAK/STAT3 signaling pathway‐mediated PD‐L1 increase in lung cancer cells was via activation of EGFR‐tyrosine kinase." (PMID 28865178, 2018). "Lung cancer cell lines treated with EGFR TKI gefitinib developed acquired resistance due to MET overexpression." (PMID 29325228, 2018). "In vitro, EGFR-mutant lung cancer cells inhibited antitumor immunity by activating the PD-1/PD-L1 pathway to suppress T-cell function." (PMID 29455650, 2018). "Lastly, future studies that link EGFR SNPs to EGFR protein expression in lung tissues are essential for understanding the mechanisms by which EGFR SNPs contribute to lung cancer." (PMID 30011810, 2018). "Our findings thus collectively suggest the therapeutic potential of NUFS‐sErt to manage the progression of a brain metastasis from an EGFR‐mutant lung cancer." (PMID 30350450, 2018). "There were several reports of dramatic intracranial response to osimertinib in patients with EGFR T790M lung cancer." (PMID 29455650, 2018). "Lung cancer where pY residues of EGFR have been exploited for treatment purpose in lung adenocarcinoma patients, but we do not have such kind of felicitously studied and catalogued data in ESCC patients." (PMID 29455652, 2018). "That the expression of sialyltransferase was up-regulated in lung cancer cell and inhibited the phosphorylation and the dimerization of EGFR." (PMID 30619732, 2018). "Liquid biopsies to genotype the epidermal growth factor receptor (EGFR) for targeted therapy have been implemented in clinical decision-making in the field of lung cancer, but harmonization of detection methods is still scarce among clinical laboratories." (PMID 29854785, 2018). "Recently, osimertinib has also demonstrated significant advantages in terms of response and progression-free survival in EGFR-mutant lung cancer patients treated in first line." (PMID 29930751, 2018). "These approaches are important milestones but however fail to account for patients who receive targeted therapy as standard of care such as EGFR inhibitors in lung cancer or BCR/ABL inhibitors in CML." (PMID 30551737, 2018). "It has been suggested that LMR has prognostic value in advanced lung cancer patients who received platinum-based chemotherapies and in advanced-stage EGFR-mutant NSCLC receiving EGFR-TKIs." (PMID 30005083, 2018). "Among unresectable advanced lung cancers, previous studies reported better responses to EGFR - TKI, progression-free survival, and overall survival in patients with 19 Del lung cancer than in those with L858R lung cancer." (PMID 30290774, 2018).